RET (ret proto-oncogene)
Diseases named in the same sentence as RET in open-access papers (continued):
Sharing a sentence is not in itself a finding about the gene and the disease.
cancer (continued). "Recent developments in RET-specific kinase inhibitors are making progress in providing considerable benefit to patients with RET-altered cancer." (PMID 33150251, 2020). "A variety of multikinase inhibitors with activity against RET have been developed and are available to treat RET-altered cancers." (PMID 33150251, 2020). "Studies have shown that the ability of TPC-1 (RET/PTC) and BCPAP (BRAFV600E mutation) cell lines to secrete CXCL8 is significantly different since oncogene types also differ in cancer cells." (PMID 32626535, 2020). "High response rates to these selective RET inhibitors across multiple forms of RET alterations in different types of cancers were observed in clinical trials, demonstrating the RET dependence in human cancers harboring these RET lesions." (PMID 35582449, 2020). "A total of 10 genes that were disrupted or within breakpoint‐associated TAD structures were classified as known (FHIT, FLCN, NCOA4, and RET) or candidate cancer genes (LLGL1, LRIG1, LYRM9, RASGEF1A, ST3GAL6, and TMEM199)." (PMID 31943436, 2020). "The high ORR of RET-selective TKIs pralsetinib and selpercatinib in RET-altered cancers unequivocally demonstrates the RET dependence of tumors carrying these RET oncogenes." (PMID 35582449, 2020). "The high response rates of pralsetinib and selpercatinib unequivocally established RET as the therapeutic target in human cancers that harbor oncogenic RET-alterations." (PMID 35582449, 2020). "Other candidates are selpercatinib or pralsetinib based on the results in lung and thyroid RET-altered cancers." (PMID 33198314, 2020). "In this study, BRAF V600E, RET/PTC1 rearrangement, and TERT promoter mutations were found to be associated with aggressive cancers 65.7% of the time." (PMID 31623671, 2019). "Further exploration revealed that RET plays a significant role in the resistance of cancer cells to endocrine treatment." (PMID 30621641, 2019). "In the following paragraph, we report the results of clinical trials involving RET related cancer patients while for preclinical data another review can be accessed." (PMID 35582269, 2019). "The evidence that RET is more expressed in ER+ than in ER- cancers is tightly correlated to the involvement of ER pathway in the development and progression of BC." (PMID 35582269, 2019). "The US pattern of DSV harboring RET/PTC rearrangements seems to be different in RET/PTC1- and RET/PTC3-positive cancers." (PMID 31717363, 2019). "Glutaminase inhibitor CB839 exhibited a more notable impact on the growth of RET-aberrant cancer cells." (PMID 31221965, 2019). "PGL/PCC development has been related to mutations in three genes that cause well-known cancer susceptibility syndromes: VHL (von hippel-lindau tumor supressor), NF1 (neurofibromin 1), and RET (ret proto-oncogene)." (PMID 31365623, 2019). "Of note, GDNF secreted by M2 polarized recruited–perineurial macrophages, activates RET on cancer cells promoting PNI." (PMID 31248001, 2019). "RT-PCR analysis revealed the presence of a RET transcript in normal mucosa and the corresponding cancer in all patients analysed." (PMID 29665843, 2018). "We conclude that there is no cancer type in TCGA that harbors an excess of damaging germline variants in DDR or cancer-relevant genes, with the exception of the well-described predisposition syndrome genes BRCA1/2, SDHB, and RET." (PMID 30217226, 2018). "Targeting EGFR using specific TKIs like gefitinib brings back cancer cells sensitivity to RET inhibitors." (PMID 29455670, 2018). "Collectively, these results provide strong support for the clinical evaluation of ponatinib in patients with RET fusion-positive cancers across 2 distinct pathological entities, NSCLC and CRC." (PMID 30038711, 2018). "As recognition of RET’s impact in diverse cancers expands, it has become an increasingly important therapeutic target." (PMID 30666215, 2018).
cancer (continued). "While RET receptor mutations are well-characterized mechanisms of carcinogenesis, the much broader implications of GFL-mediated RET signaling in cancer are only beginning to be recognized." (PMID 30666215, 2018). "Its function in promoting aggressive traits in RET-dependent cancer is reinforced by the decrease of motility and invasion after miR-182 depletion in RETM918T transformed cell lines." (PMID 28122586, 2017). "More specifically, the RET gene interacts with the Ras gene, which is involved in various cancer mechanisms." (PMID 28178311, 2017). "Zactima and Sunitinib are both clinically approved as therapeutic agents for treating cancers arising from over-activation of RET signalling." (PMID 27841748, 2016). "RET is a tyrosine kinase receptor which has been investigated as a possible target in other cancers because it is involved in oncogenic activation." (PMID 27092013, 2016). "In this scenario, the receptor tyrosine kinase RET (REarranged during Transfection) has emerged as a new player in ER+ cancer development as well as a potential target to enhance sensitivity of BC to tamoxifen therapy and to avoid tamoxifen resistance." (PMID 27034161, 2016). "This is likely due to TKI treatment of RET positive cancer exhibiting partial and different responses against aberrant forms of RET according to its fusion partners." (PMID 27150058, 2016). "As a final example, RET is a proto-oncogene that is reported to be transcriptionally up-regulated in numerous human cancers." (PMID 27539783, 2016). "To investigate RET isoform expression patterns in RET fusion-positive cancer, we screened mRNA expression levels by qRT-PCR using cDNA samples obtained from RET fusion-positive lung and thyroid cancer specimens." (PMID 27150058, 2016). "RET/PTC rearrangement is the most common genetic modification identified in this category of cancer, increasing proliferation and dedifferentiation by the activation of the RET/PTC-RAS-BRAF-MAPK-ERK signaling pathway." (PMID 27314338, 2016). "Because regorafenib inhibits the proliferation of thyroid TT cells driven by oncogenic RETC634W point mutation, we next tested the ability of regorafenib to inhibit RET fusion-positive cancer cells." (PMID 26078337, 2015). "Ectopic expression of the melanocytic gene, daupachrome tautomerase (Dct, an enzyme involved in melanin synthesis), is a sensitive and reliable marker for cancer cell dissemination in RET mice." (PMID 26575174, 2015). "Based on this knowledge, RET targeting in cancer has been exploited via the identification of small molecule RET tyrosine kinase inhibitors (TKI)." (PMID 26046350, 2015). "We focused on tyrosine kinase receptors such as EGFR, RET and c-Met genes because molecularly targeted therapies aimed at inhibiting their activities have been developed recently for several types of cancer." (PMID 25405368, 2015). "To gain information regarding the most disputed variant of RET, ATA-A Y791F, we sequenced blood DNA samples from a cohort of 2904 cancer-free elderly individuals (1261 via Sanger sequencing and 1643 via whole-exome/genome sequencing)." (PMID 25425582, 2015). "First, drugs that inhibit ALK, ROS1, and RET kinases have marked therapeutic effects on fusion-positive LADCs because the survival and growth of such cancer cells are highly dependent on the kinase activity of fusion proteins." (PMID 26437441, 2015). "We have investigated the effect of SPP86, a novel small molecule kinase inhibitor with selective activity towards RET on cancer cell proliferation." (PMID 25409876, 2014). "In total, we observed RET fusions in four of the 20 cancer types analysed, providing a therapeutic rationale for the use of RET inhibitors in multiple patient subpopulations." (PMID 25204415, 2014). "Together, these findings suggest that RET presents an attractive therapeutic target for the treatment of certain cancer subsets." (PMID 25409876, 2014).
cancer (continued). "Instead, Gattelli and colleagues show that fulvestrant induces cancer cells to produce IL-6, resulting in increased RET expression and thus creating a feed-forward RET–IL-6 expression loop." (PMID 24467886, 2014). "In this study, we further investigated the utility of SPP86 as a chemical tool for studies on RET signaling in human cancer cell lines." (PMID 25409876, 2014). "The variants found in four of the cancer genes APC, BRCA1, RET, and SDHB in our AJ centenarian sample had also been labeled as “almost certainly benign” in another sequencing study (ClinSeq) of 572 middle aged participants (17% of which are of AJ ancestry)." (PMID 25333069, 2014). "Our studies have identified SPP86 as a selective inhibitor of RET signaling in human cancer cell lines." (PMID 25409876, 2014). "Because genetic alterations in RTKs, such as FGFRs, EGFR, HER2, MET, ALK, and RET, drive human cancers, small-molecule inhibitors and human/humanized monoclonal antibodies targeted against RTKs have been developed as cancer therapeutics." (PMID 25364706, 2013). "Anti-RET aptamer exhibits anti-cancer activity in cell culture by binding to the human receptor tyrosine kinase, RET." (PMID 23130020, 2012). "We next examined expression levels of intrinsic c-Ret, Gfra1 and Gdnf transcripts in benign and malignant tumors from RET-mice." (PMID 20422010, 2010). "Thirteen of 22 (59%) adult and 10 of 21 (48%) childhood carcinomas showed evidence of RET activation, demonstrating a major role for the RET oncogene in UK thyroid papillary carcinogenesis." (PMID 8761374, 1996). "RET gain-of-function by amplification is also seen in a few cancer types." (PMID 39655713, 2025). "We synthesized alkynyl nicotinamide-based RET TKIs and tested their efficacy in cell cultures in inhibiting selpercatinib/pralsetinib-resistant RET solvent-front mutants G810C/R/S found in cancer patients, and in BaF3/KIF5B-RET(G810C) cell-derived subcutaneous and intracranial tumors in vivo." (PMID 40496186, 2025). "In addition to Selpercatinib, Pralsetinib has also shown pan-cancer efficacy across RET fusion-positive solid tumors, with an ORR of 57% (95% CI, 35–77%)." (PMID 40243903, 2025). "In this study, we have identified and demonstrated an alkynyl nicotinamide compound HSN748 as an orally available CNS-penetrant RET TKI with efficacy against selpercatinib/pralsetinib-resistant RET solvent-front mutants, showcasing promise for addressing CNS-involved RET-driven cancers." (PMID 40496186, 2025). "Aberrant activation of RET has been observed in various types of human cancer." (PMID 41373459, 2025). "In this sense we should highlight that RET gene rearrangement, particularly RET/PTC, is highly specific for papillary thyroid carcinoma and is associated with the characteristic nuclear features seen in this type of cancer." (PMID 39744583, 2025). "In RET-mutant cancers, Vandetinib acts as an anti-angiogenetic and an antineoplastic drug." (PMID 40332222, 2025). "Abnormally activated RET signaling is recognized as a critical inducer of several human cancers." (PMID 40725174, 2025). "These dual pathologies underscore the importance of comprehensive genetic and molecular analysis, as shared mutations like RET or BRAF may drive their concurrent occurrence and be associated with other cancers." (PMID 40677447, 2025). "However, delta‐He has been inadequately explored in the context of cancer, whereas the iron metabolism‐related marker, RET‐He, has primarily been evaluated in the context of cancer‐related anemia." (PMID 40186416, 2025). "However, the success of these inhibitors in other cancer types suggests potential applicability, especially in cases where RET alterations are identified." (PMID 39925808, 2025). "Loss-of-function RET mutations are primarily associated with developmental disorders rather than cancer." (PMID 41465145, 2025).
cancer (continued). "However, the development of selective RET inhibitors, such as Selpercatinib and Pralsetinib, has been advantageous in the pan-cancer treatment setting and received FDA approval due to improved specificity and potency." (PMID 40243903, 2025). "However, each TKI has different inhibitory activities against its various targets and consequently exerts distinct therapeutic effects on RET-related cancers." (PMID 40725174, 2025). "These alterations contribute to the progression of diverse cancers where RET function is disrupted." (PMID 39086985, 2024). "Low expression of thymidylate synthase may explain an increased sensitivity of ALK-, ROS1- and RET-driven cancers to pemetrexed." (PMID 38966170, 2024). "Since the drug has also shown efficacy on RET-wildtype tumors, it may also be useful in patients with RET overexpressing cancers." (PMID 39931212, 2024). "Lung cancer is among the most common cancer types in the world, with the majority of subjects presenting with metastatic spread; therefore, this disease is definitively the main source of patients requiring treatment by RET inhibitors." (PMID 38612902, 2024). "By understanding the landscape of RET kinase inhibitors and using computational methodologies, we aim to translate these insights into clinical practice, ultimately enhancing patient outcomes and revolutionizing cancer treatment paradigms." (PMID 39086985, 2024). "In light of this, the authors hypothesized that some RET-positive cancers could be evaluated using FDG-PET, allowing for a qualitative assessment of treatment response." (PMID 39272672, 2024). "Of these 11 non-MTC cancers with a RET splice variant, eight harbored RET 2/8, six had RET 2/4, and six had both splice variants." (PMID 38566816, 2024). "KEGG analysis showed that cytokine-cytokine receptor interaction, cell adhesion molecules, and transcriptional misregulation in cancer may play a role in nodal metastasis triggered by RET alteration." (PMID 38734621, 2024). "It is not known what the exact mechanisms are which could explain the brain tropism of RET fusion-positive NSCLC cancers." (PMID 39199650, 2024). "We demonstrated that driver genes (BRAF, RET and TERT, etc.)are co-mutated with other genes, such as DNA damage repair genes and metabolism related genes, thus forming a co-mutation pattern observed more frequently in cancer tissues than benign nodules." (PMID 38886866, 2024). "In addition, CDX2-suppressed cancers had a higher prevalence of mutations in several receptor tyrosine kinase genes, including EGFR, ERBB3, ERBB4, RET, and ROS1." (PMID 39452477, 2024). "Additionally, we present compelling case studies showcasing the application of RET inhibitors in the treatment of patients afflicted with RET-positive cancers." (PMID 39272672, 2024). "However, the abnormal activation of RET frequently results in oncogenesis, making it an important therapeutic target for various cancers." (PMID 38397034, 2024). "Moreover, comprehensive data from the LIBRETTO-001 trial have led to its groundbreaking tissue-agnostic FDA approval for RET-fusion-positive cancers, underscoring the impact of selpercatinib in the field of precision oncology." (PMID 39085487, 2024). "The clinical efficacy of selective RET inhibitors in RET-positive cancers has been remarkable." (PMID 39272672, 2024). "Key targeted therapies include RET inhibitors like selpercatinib for RET rearrangements, ALK inhibitors like alectinib and crizotinib for ALK gene alterations, and EGFR inhibitors like osimertinib and erlotinib for EGFR-mutated cancers." (PMID 39457373, 2024). "This suggests that RET inhibitors plus immunotherapy may be the ideal treatment for malignant tumors, which certainly need further clinical studies." (PMID 38734621, 2024). "RET fusions have a frequency of <1% across multiple cancers." (PMID 39061168, 2024).
cancer (continued). "More recently, cancer cells exhibiting high small-cell neuroendocrine phenotype scores have demonstrated a strong dependency on RET kinase activity, with a significant correlation between RET and ZBTB7A dependencies." (PMID 39682746, 2024). "Therefore, this study aims to discover effective lead compounds targeting RET across different cancer types and evaluate their potential to inhibit cancer progression." (PMID 39086985, 2024). "This novel approach revealed valuable insights into the treatment response of RET positive cancers." (PMID 39272672, 2024). "However, increasing evidence indicates that RET is also involved in tumor growth and metastasis across various cancer types." (PMID 39399471, 2024). "Downregulation of claudin-1 with various strategies, including PKC inhibition, C. perfringens enterotoxin, RET inhibition, or exogenic delivery of anti-cancer miRNA, may be beneficial in the case of PTC, FTC, and MTC." (PMID 39458944, 2024). "RET rearrangements have been detected in a variety of human cancers." (PMID 38297314, 2024). "This retrospective study included 86 stage IV NSCLC patients harboring RET rearrangement from six cancer centers between May 2017 and October 2022." (PMID 38349001, 2024). "Furthermore, most of the CIC steps, including priming and activation (Step 3) as well as trafficking of immune cells to tumors (Step 4) were activated in PTC with RET alteration, whereas recognition of cancer cells (Step 6) was suppressed." (PMID 38734621, 2024). "Incorporating FDG-PET into the assessment of selective RET inhibitor responses may provide valuable insights into the metabolic changes within tumors and aid in treatment decision making for patients with RET-positive cancers." (PMID 39272672, 2024). "Moreover, the phase 2 pediatric MATCH trial (NCT04320888; NCT03155620) is studying selpercatinib in RET-altered cancers in the pediatric patient population (⩽21 years)." (PMID 37360768, 2023). "An assay that targeted 244 cancer-related genes detected RET fusion in 4.35% PTC." (PMID 36865807, 2023). "However, multiple studies are currently ongoing to explore the expanded potential of selpercatinib in RET fusion-positive cancers." (PMID 37360768, 2023). "Due to the high prevalence of RET mutations in MTC, the inhibition of EGFR may indirectly provoke cancer activity." (PMID 36768635, 2023). "TPX-0046 presents perfect benefits in vitro and in vivo RET fusion cancers." (PMID 36865807, 2023). "Furthermore, the LPCs derived from RETC634Y iPSCs exhibited a positive response to the RET inhibitor pralsetinib, evidenced by the downregulation of the cancer markers." (PMID 38132167, 2023). "Multi-kinase inhibitors, such as Cabozantinib, Vandetanib, and Lenvatinib, have demonstrated efficacy in the treatment of RET fusion-positive cancers, but their lack of specificity and susceptibility to drug resistance have been noted." (PMID 37375228, 2023). "Moreover, this study has allowed proposing 36 candidate susceptibility cancer variants in a total of 10 families (seven NMTC families and three non-RET MTC families)." (PMID 37175550, 2023). "Numerous studies have shown that the PI3K/AKT/mTOR pathway is an essential signaling pathway that is activated by the oncogenic RET, which subsequently promotes the survival of cancer cells through the phosphorylation of mammalian target of rapamycin (mTOR) protein." (PMID 37046823, 2023). "RET fusion is a one of common genetic drivers in multiple human cancers, including PTC." (PMID 37081420, 2023). "In particular, we used a specific anti-miRNA that targets miR-21 to suppress the expression of miR-21, examining the possible effects on two reference cancer cell lines for MTC: TT cells carrying a RET C634W mutation and MZ-CRC-1 cells carrying a RET M918T mutation." (PMID 37361540, 2023). "Major advanced were made recently in the field of targeted therapy for RET-altered cancers." (PMID 37081420, 2023).